TRGJ2 (T cell receptor gamma joining 2)
Synonyms: J2; TCRGJ2
Gene: T-cell receptor joining (J) gene on chromosome 7 (38,253,380 to 38,253,429, reverse strand). Ensembl gene ENSG00000211687.
Diseases named in the same sentence as TRGJ2 in open-access papers:
TRGJ2 is named in the same sentence as 1 disease in open-access papers, as found by Europe PMC text mining. Sharing a sentence is not in itself a finding about the gene and the disease.
TRGJ2 shares sentences with these, for which no sentence is quoted: psoriasis (1 paper).